MMP2 (matrix metallopeptidase 2)
Diseases named in the same sentence as MMP2 in open-access papers (continued):
Sharing a sentence is not in itself a finding about the gene and the disease.
cancer (continued). "Fibroblasts in the stroma of the bone secrete matrix metallopeptidase-2 (MMP2) in an inactive state and have been shown to promote bone metastasis in the presence of cancer cells, which activates MMP2." (PMID 30871004, 2019). "Paris saponin VII (PS VII), extracted from Trillium tschonoskii Maxim, inhibits the migration and invasion of several types of cancer cells via the downregulation of MMP-2 and -9 expression and p38 MAPK phosphorylation in a dose- and time- dependent manner." (PMID 31781485, 2019). "Acacetin also blocked the phosphorylations of Stat-1 (Tyr701) and Stat-3 (Tyr705), as well as restrained the expression levels of pro-angiogenic factors, e.g. VEGF, eNOS, iNOS, MMP-2 and bFGF, in cancer cells." (PMID 32009958, 2019). "The expression level of two enzymes linked to cancer cell invasion (matrix metalloproteinase (MMP)-1 and MMP-2) was measured in LDD-1819 treated breast carcinoma cells using qPCR." (PMID 31489353, 2019). "Intriguingly, interaction of MMP2 and αVβ3-integrin on the cell surface of cancer cells has been shown to induce the downstream PI3K/AKT signaling pathway." (PMID 31319863, 2019). "This suggests that MMP-2 not only accelerates the proliferation of cancer cells, but is also closely related to tumor invasion and metastasis." (PMID 31514467, 2019). "In our study, performed on paired tissues from NSCLC patients, the MMP2 expression was on comparable level in cancer tissue and NLNT." (PMID 31921636, 2019). "Further study that examines how NAB2 increases MMP2 in a cancer microenvironment, the expression of CAF markers in fibroblast cells is particularly needed." (PMID 30893927, 2019). "Of these, MT1-MMP (membrane type-1 matrix metalloproteinase, MMP14) is a key protease that activates pro-MMPs such as MMP2 and MMP9 and is associated with ECM degradation and cell migration during cancer metastasis." (PMID 31223610, 2019). "Matrix Metallopeptidase 2 (MMP-2) plays a key role in the promotion of cancer invasion and metastasis through the degradation of ECM to allow cancer cells to move around." (PMID 31217907, 2019). "The p16INK4a as an inhibitor of Cdks have been shown to diminish SP-1 binding at MMP-2 promoter and reduced migration of cancer cells via downregulation of MMP-2." (PMID 30646538, 2019). "AKT, an important signalling molecule downstream of PI3K, plays a key role in the invasion of cancer cells by regulating MMP-2, which regulates the migration and metastasis of cancer cells by degrading the extracellular matrix." (PMID 31591377, 2019). "MiR-101 inhibits cancer-associated fibroblast (CAF)-promoted VM in HCC cells through a novel regulatory network, which involves the TGF-β and SDF1-mediated VE-cadherin/MMP-2/LAMC2 signaling pathway." (PMID 31772665, 2019). "Consistently, there was a significant negative correlation between hepatic cyclin D1 gene expression and cell death and a significant positive correlation between cyclin D1 expression and cancer metastatic capability (as assessed by the MMP-2:TIMP-1 ratio)." (PMID 31836811, 2019). "To investigate the role of MMP-2 in the spatiotemporal evolution of the cancer cells, we varied both the MMP-2 production rate and the MMP-2 diffusion coefficient." (PMID 30903592, 2019). "The interaction between HA and CD44v6 modifies ECM components to support the invasiveness of cancer cells by stimulating the production of matrix metalloproteinase 2 (MMP2) and MMP961,62." (PMID 30631039, 2019). "Multiple GO terms were enriched associated with MMP-1, MMP-2, MMP-9 and VEGF, and they are closely associated with pathways, proteoglycans and microRNAs related to cancer." (PMID 31311559, 2019). "It has been reported that MMPs are major components involved in metastasis, especially, the increased MMP2 and MMP9, two important members of MMPs, are associated with cancer aggressiveness and metastasis in TNBC." (PMID 31186039, 2019).
cancer (continued). "In agreement with our data, low-density lipoprotein receptor-related protein-1 (LRP-1) and ApoE-binding receptors promote cancer cell migration via induction of MMP-2 and MMP-9 expression, and are involved in inducing cyclin D1 in interstitial fibroblasts." (PMID 31275318, 2019). "The p38 MAPK also acted as a negative regulator during angiogenesis and played an important role in inhibiting cell migration and invasion by downregulating MMP-2/MMP-9 secretion in cancer cells." (PMID 31293977, 2019). "In the AC subtype, there were also observed the positive correlations between TIMP3 in NLNT and MMP2 levels, both in cancer and NLNT (R = 0.699, p < 0.001, and R = 0.500, p = 0.021, respectively; rs)." (PMID 31921636, 2019). "β-catenin and MMP-2 play critical roles in cancer cell invasion and metastasis and these proteins are overexpressed in cancer." (PMID 31119174, 2019). "Following these morphological changes, the cancer cells become migratory and invasive due to an enhanced expression of matrix metallopeptidase 2 (MMP-2) and matrix metallopeptidase 9 (MMP-9)." (PMID 31216782, 2019). "MMP-2 was also observed in diverse cancers, such as breast, brain, ovarian, pancreas, colorectal, bladder, prostate and lung cancer." (PMID 30696858, 2019). "For MMP-2, it is 1.46 ± 0.77 fold lower in cancer compared to normal for Chinese and US tissues combined, and it is 1.44 ± 0.12 fold lower in cancer compared to normal in Chinese tissue." (PMID 30917169, 2019). "It has previously been reported that MMP-2 is secreted as a zymogen (pro-MMP-2), and that membrane-bound MMP-14 (MT-1-MMP), which is mainly expressed on fibroblasts and cancer cells, activates secreted MMP-2 by cleaving its pro-domain." (PMID 31726690, 2019). "The reduced p16INK4a nuclear localization by overexpression of hYSK1 leads to the activation of SP-1 transcriptional activity, resulting in increased MMP-2 expression and enhanced cancer cell proliferation and migration." (PMID 30646538, 2019). "FAK-dependent induction of MMPs is not limited to cancer; in tenocytes the mechano-growth factor promotes MMP-2 secretion and cell invasion in a manner dependent on FAK and ERK kinases." (PMID 31671408, 2019). "Considering only normal or only cancer tissue, MMP-2 expression is 1.53 ± 0.13 (P < 0.005) higher normal tissue and 1.41 ± 0.12 (P = 0.05) higher in cancer tissue, in Chinese compared to US." (PMID 30917169, 2019). "It appears that decreased invasion of cancer cells is a consequence of MMP-2 and MMP-9 down-regulation." (PMID 31569687, 2019). "(2009) used a homogeneous HT-1080 cancer cell population, and thus cells of mesenchymal origin, in their experiments to examine the role of MT1-MMP and MMP-2 in cancer invasion." (PMID 30903592, 2019). "The extract inhibited aggressiveness of the cancer cells by inhibiting characters of metastasis such as cell motility, adhesion, invasion and reduced MMP-2 and 9 expressions." (PMID 31601896, 2019). "MMP2 degrades cellular matrix components and the basement membrane, and therefore reduces the barriers for cancer cell migration and/or invasion." (PMID 31811115, 2019). "In short, the collaborative work of CCR1, MMP9, and MMP2 at metastatic sites promotes cancer metastasis." (PMID 31474975, 2019). "Previous studies have shown that the MMP-2 (-1306C/T) and TIMP-2 (-418G/C) polymorphisms are involved in the development of many cancers, such as breast, lung, and esophageal and colon cancer." (PMID 31032338, 2019). "This included the EMT-inducing zinc-finger E-box-binding homeobox factor (ZEB2) and the STAT3 target MMP2, which enhances the degradation of extracellular matrix proteins and cancer cell invasion." (PMID 30645971, 2019). "Ceteris paribus, we then re-examined the effectiveness of invasion involving solely MT1-MMP as well as solely MMP-2 in a system with haptotaxis-dominated cancer cell movement." (PMID 30903592, 2019).
cancer (continued). "A relationship seems to exist between MBP-1 expression and the decrease in the activity levels of MMP-9 in cancer tissues and MMP-2 in sera." (PMID 31416219, 2019). "Large GNPs can be degraded by matrix metalloproteinases-2 (MMP-2) overexpressed in cancer, while small NPs decorated with RGD peptide can easily penetrate deeply into tumor tissues." (PMID 31072061, 2019). "This dependence suggests a lower impact of metalloproteinase-9 on the invasion ability of cancer into the stroma, particularly at a high degree of nodal staging, where the main role is played by the increase in MMP-2 expression." (PMID 31223594, 2019). "It should be noted that while prior studies of MMP-2 protein described increases in cancer compared to normal for human prostate, studies which measure transcript levels, as we are currently doing, have shown opposite findings." (PMID 30917169, 2019). "Metalloproteases secretion, in particular MMP-2 and MMP-9, is linked to invasive and metastatic properties of cancers cells." (PMID 31671408, 2019). "An alternative treatment proposed in an in vitro study uses a combination of temozolomide and compounds 1 and 2 of N-O-isopropyl sulfonamido-based hydroxamates (MMP-2 inhibitors) to inhibit cancer cell invasiveness and viability." (PMID 31921634, 2019). "For example, it appears that soluble BSG, shed from the cell surface of cancer cells, acts in a paracrine manner to stimulate the expression of MMP2 in the surrounding stromal fibroblast." (PMID 31013576, 2019). "The association of the MMP-2 (-1306C/T) and TIMP-2 (-418G/C) polymorphisms with the incidence and development of many cancers has been widely reported." (PMID 31032338, 2019). "As MMPs are important in regulating cancer cell invasion and migration, we further examined the protein levels of MMP-2 and MMP-9 in SACC-83 and SACC-LM cells." (PMID 31762692, 2019). "We have identified several microRNAs (miRNAs) to elucidate the molecular link how AXT inhibits cancer cell metastasis by repressing MMP2 and ZEB1 expression." (PMID 31263239, 2019). "In AD, Rab5 is overactivated, leading to TrkB downregulation, while in cancer its overexpression influences either FAK or ERK/MMP2 pathways." (PMID 31426400, 2019). "We next investigated the roles of MT1-MMP and MMP-2 in cancer cell invasion in the scenario of haptotaxis-dominated cancer cell movement." (PMID 30903592, 2019). "badia and Arbutus unedo present a lectin-like inhibitory action on cancer cell migration and MMP-2 and MMP-9 activity in HT29 cancer cells, which is unique to this subspecies, and which can be potentially used as an anticancer-agent." (PMID 31234551, 2019). "Stimulated MMP-2 production in co-culture of cancer cells and fibroblasts was completely suppressed by siRNA knockdown of CD73, but not by CD99 knockdown." (PMID 31510956, 2019). "Among these proteases, a transmembrane MMP, MMP-14 (MT1-MMP), has been shown to be a master regulator of invadosome function and to cleave and activate pro-MMP-2, which is transported to the forming invadosomes during cancer cell invasion." (PMID 30818851, 2019). "At molecular level, cancer progression factors MMP2 and MMP9 are induced in response to RBP4 overexpression." (PMID 29642915, 2018). "Genes regulated by TH-binding to integrin αvβ3 include fibroblast growth factor 2 (FGF2), matrix metalloproteinase 2 (MMP2), HIF1A, and cyclooxygenase 2 (COX2), which have been associated with cancer development and angiogenesis." (PMID 30360449, 2018). "In conclusion, MMP-2-PLGA-PEI nanoparticles are an effective tool to visualize dynamic MMP-2 activities of potential metastatic cancer cells." (PMID 29466303, 2018). "MMP-2 and MMP-9 are both secreted, cancer-associated, zinc-dependent endopeptidases, which play key roles in regulation of some crucial signaling pathways in cell growth, invasion, migration, angiogenesis, and inflammation." (PMID 29899165, 2018).
cancer (continued). "The matrix metalloproteinases (MMPs) are crucial in promoting cancer cell invasion by degrading cellular matrix components and the basement membrane, and our previous work showed that MMP-2 is crucial for BC invasion." (PMID 30195772, 2018). "We have shown that knock-down of HUGL1 in human mammary epithelial cells leads to upregulation of five transcripts that have been linked to cancer stem cells, side population (SP) cells, or increased invasion in cancers (ABCG2, MMP2, ESR1, THBS1 and KRT19)." (PMID 29361610, 2018). "On the other hand, CAF-derived exosomes have been found to enhance migration and invasion of gastric cancer cells by inducing MMP2 expression in the cancer cells." (PMID 29883428, 2018). "This research demonstrated that MMP-2-PLGA-PEI nanoparticles were able to accurately detect MMP-2 activity of cancer cells." (PMID 29466303, 2018). "The PI3K/AKT signalling pathway promotes cancer cell invasion through up-regulation of MMP2 via multiple pathways." (PMID 30123092, 2018). "Since it has been reported that the anti-inflammatory agent dexamethasone inhibits MMP-2 expression and cancer cell migration, we examined the effect of dexamethasone on ATRA-induced MMP-2 secretion in THP-1 cells." (PMID 30225259, 2018). "The small GTP-ase Rac promotes invasion and has been shown to regulate S1P-evoked matrix metalloproteinase 2 and -9 (MMP2 and -9) secretion in cancer cells." (PMID 29734379, 2018). "Owing to the important role of proteinases such as MMP-2 and uPa in the cancer invasion process, we investigated their expression by cancer cells in the presence of VG-6 or AG-9." (PMID 29707150, 2018). "Based on this, target MMP-2 expression in cancer cells is a reasonable strategy for decreasing metastasis, and the use of dietary compounds, in particular curcumin, has gained attention." (PMID 29385675, 2018). "MMP-9 and MMP-2 are recognized as playing a vital role in cancer cell invasion and metastasis among the MMP family." (PMID 29565268, 2018). "The epigenetic loss of DKK3 expression activates TGF-β signaling, leading to increased expression of pro-invasive factors, such as TGFBI and MMP2, which have the potential to promote progression to cancer." (PMID 29858602, 2018). "Studies have shown that the PI3K/AKT signaling pathway plays an important role in invasion and distant metastasis of cancer through MMP-2 and MMP-9 regulation." (PMID 29977159, 2018). "Recently, It is well known that matrix metalloproteinases (MMP) especially MMP-2/9 played vital roles in cancer progression." (PMID 29357836, 2018). "Amplified in breast cancer 1 (AIB1) can also regulate MMP-2 expression via the co-activation of PEA3 (polyoma enhancer activator protein) transcription factors that bind to the MMP-2 gene promoter." (PMID 29874869, 2018). "Our results suggest that the MMP-2-PLGA-PEI nanoparticles are a promising tool for visualizing the dynamic MMP-2 activities of potential metastatic cancer cells." (PMID 29466303, 2018). "Ratiometric activatable cell penetrating peptides (RACPPs) previously used to image cancer based on MMP-2/-9 activity were used to understand differences in MMP activity in WT or knockout syngeneic tumors in WT and KO animals." (PMID 30248101, 2018). "In this study, the selectivity and cytotoxicity of MAHNP-DOX for cancer cells and tumors is mainly realized by the MMP-2 sensitive peptide linker." (PMID 29405790, 2018). "Intensified motility of the cancer cells was mediated by PI3K/Akt-related signaling and associated with the hyperactivity of MMP-2." (PMID 28956065, 2018). "MMP-2 is a critical factor that regulates cancer metastasis, and appears to affect cell migration and invasion by affecting ERK1/2 and NF-κB signaling." (PMID 30359388, 2018). "NAR is known to inhibit MMP-2 and -9 as well as reduce the AKT activity in A549 cells, thereby causing cancer cell apoptosis." (PMID 29534519, 2018).
cancer (continued). "To date, there has been substantial evidence indicating stronger signals for MMP-2 in stromal cells compared to cancer cells, while stromal fibroblasts interact with cancer cells by secreting and activating MMP-2." (PMID 29405790, 2018). "The down-regulation of FAK and MMP-2 expression was involved in the inhibition of Xn on migration and invasion of cancer cells." (PMID 29872398, 2018). "Studies have confirmed that many early-stage cancers express elevated levels of MMP-2, MMP-3, and MMP-9." (PMID 29390034, 2018). "This indicates that actein can upregulate the expression of inhibitors TIMP-1 and TIMP-2 but downregulate the expression of MMP-9 and MMP-2, thereby resulting in the suppression of cancer metastasis." (PMID 30618758, 2018). "We further investigated the effect of CASZ1 on the expression of several genes related to cancer cell proliferation and invasion, such as MMP2, MMP9, cyclinD1 and epithelial-mesenchymal transition (EMT) genes, which were controlled by the MAPK/ERK pathway." (PMID 29506567, 2018). "It has been reported that poor prognosis in several patients with cancer correlates with the increased activity of MMP-2 and MMP-9." (PMID 30336548, 2018). "Stat3 and Src/FAK/Rac1 signal are known as an vital role in controlling cell migration and invasion by regulating the expression level of genes included MMP2, 9 and it is established that the level of MMPs is positively related to cancer cell metastasis." (PMID 29423083, 2018). "To exclude the contribution of secretion of MMP-9 and MMP-2 from cancer cells, we established MMP-knockdown cells by the RNA interference procedure." (PMID 30544870, 2018). "ECM remodeling is a major event promoting cancer invasion and metastasis; where matrix metalloproteinases (MMPs) such as MMP-2, -9, -11, and -14 play vital roles degrading the matrix proteins for cancer spread." (PMID 29983921, 2018). "Pieces of evidence have indicated that the activated IGF-1R translocates to the nuclei of several human cancer cells and regulates, by acting as a transcription regulator, cancer cell migration through the modulation of MMP-2 expression." (PMID 29690502, 2018). "In all of these studies, authors have showed that platelet and cancer cell MMP-2 cell surface expression contribute to TCIPA." (PMID 30441823, 2018). "Our previous studies on human carcinoma demonstrated that the EGCG+IIF combination was very effective in decreasing the expression of MMP-2 and MMP-9, which are molecular markers of invasion." (PMID 30135355, 2018). "As copper, CD147, MMP-2 and MMP-14 are all implicated to promote the metastasis of cancer, our study sheds light upon their functional mechanisms and relationship in cancer progression." (PMID 28881637, 2017). "MMP-2 plays an important role in the early detection of cancer due to its over expression on cancer cells compared to healthy cells." (PMID 28492519, 2017). "MMP-2 is an established pro-migratory protease that participates in cancer migration and invasion, suggesting that TSP-2 regulates MMP-2 followed by modulating migration and invasion in PCa cells." (PMID 28122633, 2017). "First, many researches showed that high expression of MMP-2 and MMP-9 proteins are related with prognosis caused by cancer metastasis." (PMID 28350337, 2017). "MMPs therefore represent the potential target for preventing cancer metastasis, especially targeting for MMP‐2." (PMID 28672103, 2017). "Metastasis process involves invasion and migration of cancer cells and enzymes like MMP-2/MMP-9 play a major role in this process." (PMID 28724926, 2017). "Two such targets are matrix metalloproteinases-2 and -9 (MMP-2, −9), which degrade extracellular matrix as a prerequisite for cellular invasion and have been shown to be involved in other types of cancer metastasis." (PMID 28633655, 2017).